SRF (serum response factor)
Diseases named in the same sentence as SRF in open-access papers (continued):
Sharing a sentence is not in itself a finding about the gene and the disease.
tumor (continued). "The expected similarities and conservation of SRF’s and IGF2BP1’s roles in modulating tumor cell properties suggested that the post-transcriptional regulator IGF2BP1 synergizes with the transcriptional regulator SRF in promoting an ‘aggressive’ tumor cell phenotype." (PMID 30371874, 2019). "In addition, EMT involvement in oncogenesis or tumour malignancy is controlled by various EMT regulators, including N-myc, ZEB1/2, Snail, Slug, Twist, SRF, and β-catenin." (PMID 28727734, 2017). "Interestingly, in L108 it was also possible to see the subclonality of this event: while the SRF rearrangement was observed only in a subpopulation of the cells, FUS rearrangement was observed in almost all tumor cells (92%)." (PMID 28947952, 2017). "We also evaluated possible correlations between the expression of SRF and α-smooth muscle actin (α-SMA) in tumor cells with the clinicopathological characteristics of ESCC, including gender, age, tumor diameter, histological grade, lymph node metastasis and depth of invasion." (PMID 23426188, 2013). "The rise in CRNDE levels during neoplasia may be a response to perturbations in upstream signaling pathways, for example the MAP kinase pathway, which among other actions mediates SRF activity." (PMID 23226159, 2012). "However, in both human and mouse, smooth muscle cells that lack SRF exhibit an increased propensity to enter senescence, while MRTF–SRF signalling suppresses oncogene-induced senescence in cancer cells lacking the tumour suppressor DLC1, a RhoGAP." (PMID 41200793, 2025). "IGF2BP1 promotes SRF expression in a conservative m6A-dependent manner by impairing the decay of SRF mRNA guided by miRNA, thereby promoting the expression of genes such as PDLIM7 and FOXK1 that can promote tumor cell growth, ultimately promoting tumor cell growth and invasion." (PMID 39062595, 2024). "At 100 mg/kg bw/day, BPAF resulted in the significant upregulation in gene expression of seven targets (GPER1, JNK, Akt, Fos, FOXO1, PDZK1, SRF), while the gene expression of the other 12 targets were not significantly changed compared to the SK-BR-3 bearing tumor control." (PMID 36497816, 2022). "Serum response factor (SRF), a member of the MADS box superfamily of transcription factors, could promote tumor metastasis by enhancing the proliferation, invasion, and angiogenesis of tumor cells." (PMID 36286020, 2022). "In terms of tumor subtype, the following are found: 2 alveolar; 3 spindle cell/sclerosing, 6 embryonal RMS, and finally 3 cases described as a homogenous type of well-differentiated RMS, characterized by specific translocations of the SRF (Serum Response Factor) gene." (PMID 36173721, 2022). "In addition, IGF2BP1 was reported to impair the miRNA-directed decay of the SRF mRNA and then promote the expression of SRF in a m6A-dependent manner, sustaining the expression of PDLIM7 and FOXK1, which promotes tumor cell growth and cell invasion of ovarian cancer." (PMID 33611339, 2021). "Specifically, by promoting the expression of serum response factor (SRF) in an m6A-dependent manner via impairing the miRNA-dependent decay of the SRF mRNA, IGF2BP1 promotes SRF-dependent transcription in cancer, thereby enhancing tumor cell growth and invasion." (PMID 34692544, 2021). "However, even if preliminary, these results indicated that the chimeric protein could retain DNA binding specificity of SRF and through the trans activation domain of E2F1 is able to activate SRF target genes, probably supporting tumor growth." (PMID 28947952, 2017).
tumor (continued). "Since IL6 cytokine is also expressed in immune cells, xenografts from immune-deficient mice may not faithfully reflect the in vivo significance of SRF–YAP–IL6 signalling in tumour initiation." (PMID 26671411, 2015). "This relationship was confirmed in patients’ tissue samples, with a negative correlation between AR and SRF expression in CRPC bone metastases and a positive correlation in androgen-naïve primary tumours." (PMID 33260953, 2020). "This revealed that IGF2BP1 also serves SRF-independent roles in cancer cells and thus supports the notion that IGF2BP1 promotes an ‘aggressive’ tumor cell phenotype via pleiotropic effectors." (PMID 30371874, 2019). "In contrast, SRF inactivation induces apparent senescence in smooth muscle cells and activates oncogene-induced senescence in cancer cells lacking the DLC1 tumour suppressor, a RhoGAP." (PMID 41200793, 2025). "Tumour cells lacking RASSF1A expression display high levels of nuclear actin/profilin, reduced MRTF‐A levels and low transcription of SRF target genes, including SRF itself." (PMID 31414556, 2019).
cancer (114 papers, 2009 to 2025). A tumor composed of atypical neoplastic, often pleomorphic cells that invade other tissues. "These inhibitors prevent MRTF nuclear localization and its interaction with SRF, thus inhibiting MRTF/SRF-mediated transcription linked to fibrosis and cancer progression." (PMID 39996739, 2025). "Cooperation between YAP1/TAZ and SRF was reported for the differentiation of vascular SMCs but also in certain cancer cells and cancer-associated fibroblasts." (PMID 39155965, 2024). "The discovery of a novel series of oxadiazole-thioether CCG-molecules, inhibitors of the Rho/MRTF/SRF transcription pathway, has implicated their role in preventing cancer cell migration in vitro and improving fibrosis in vivo." (PMID 38474356, 2024). "This suggested that potentially ‘oncogenic’ effectors of SRF/IGF2BP1 are identified by a conserved positive association with SRF/IGF2BP1-expression in cancer and downregulation upon SRF and IGF2BP1 depletion in cancer-derived cells." (PMID 30371874, 2019). "In this study, we identify the SRF-encoding (serum response factor) mRNA as a conserved target mRNA of IGF2BP1 in cancer." (PMID 30371874, 2019). "The majority of transcripts enhanced by SRF/IGF2BP1 in ES-2 cells show a conserved association with SRF/IGF2BP1-expression in cancer." (PMID 30371874, 2019). "Two of these 35 mRNAs, PDLIM7 and FOXK1, showing a significant and positive association with both, IGF2BP1 and SRF expression in cancer, as indicated for HCC and EOC, were chosen for validating regulation by IGF2BP1 and SRF." (PMID 30371874, 2019). "Mechanistically, MBZ can modulate the cancer-associated pathways including ELK1/SRF, AP1, STAT1/2, MYC/MAX, although the regulatory outcomes are context-dependent." (PMID 28099902, 2017). "We analyzed the effect of monensin on 11 cancer-associated pathways and found that monensin inhibits the reporter activities for the Elk1/SRF, AP1, NFκB and STAT pathways, and to a lesser extent the Myc/Max reporter activity." (PMID 26639992, 2015). "CCG-1423 and related analogues represent a new class of inhibitors of Rho/MKL1/SRF-mediated gene transcription, a pathway that has been implicated in both cancer and fibrosis." (PMID 23766813, 2013). "Pan-cancer analysis revealed a significant positive association between SRF and MCM4." (PMID 40959096, 2025). "Moreover, the importance of SRF in promoting cancer-associated processes, such as cell proliferation, invasion, and metastasis, is increasingly recognized." (PMID 37266453, 2023). "For instance, both Bcl6 and the MKL/SRF complex are linked to the development of cancer, and the interaction of these two pathways could lead to drug resistance." (PMID 37967194, 2023). "Moreover, the migratory process is sustained by the cooperation of YAP and TAZ with myocardin-related transcription factor (MRTF) and serum response factor (SRF) for the activation of cancer-associated fibroblasts, matrix stiffening, and metastasis." (PMID 34205830, 2021). "Moreover, MRTF and SRF have been implicated in cancer cell motility regulation by modulating the construction of actin filament networks." (PMID 32665796, 2020). "MRTF-A and SRF have been shown to activate gene expression of proteins associated with focal adhesions in fibroblasts and are associated with migration and invasion in a cancer cell line." (PMID 31191527, 2019). "Therefore, upregulation of SRF may serve as the suppressive mechanism underlying attenuation of HGF seen in LIUS treated non-cancer cells." (PMID 31355136, 2019). "These interactions need to be examined further, especially in the context of cellular differentiation, stress responses, or disease states such as cancer or neurodegeneration, where both SRF and RNA processing pathways play critical roles." (PMID 40869995, 2025).
cancer (continued). "These interactions need further exploration, especially in the context of cellular differentiation, stress response, or disease states such as cancer or neurodegenerative disease, where SRF as well as RNA processing pathways are of central importance." (PMID 40869995, 2025). "The breakthrough findings of the importance of RhoA/MRTFs/SRF transcription in cardiovascular, neurodegenerative, and intestinal diseases and fibrosis to cancer tumorigenesis and metastasis have been much appreciated." (PMID 38474356, 2024). "Another m6A binding protein, IGF2BP1, promotes serum response factor expression in an m6A-dependent manner by impairing the miRNA-directed downregulation of the serum response factor (SRF) mRNA in cancer cells." (PMID 36614216, 2023). "Functionally, SRF or YAP inhibition causes a reduction in PCa cells’ anchorage-independent growth ability, a critical feature of later stage cancer development." (PMID 37385752, 2023). "Activation of SRF-MRTF, as well as SRF independent MRTF activation are important mediators of mechanical forces essential for cancer cell migration through dense extracellular matrix." (PMID 36147738, 2022). "MRTFs in association with SRF are key TFs regulating muscle machinery adaptation to workload, and along with YAP-TAZ, impart contractile properties to cancer associated fibroblasts." (PMID 36147738, 2022). "SRF mRNA is protected from miRNA-mediated degradation via Igf2bp1 binding, and SRF and Igf2bp1 synergize to promote gene expression in cancer." (PMID 34895045, 2022). "The resulting depletion of nuclear G-actin drives transcription of Myocardin-related transcription factor (MRTF)/serum-response factor (SRF)-target genes to implement cell scattering and the invasive behaviour of cancer cells." (PMID 34819513, 2021). "Myocardin-related transcription factor A or megakaryoblastic leukemia 1 (MKL1) is a transcriptional coactivator of serum response factor that has been shown to promote cancer cell migration and invasion." (PMID 32156248, 2021). "Particularly, it will be important to investigate the epigenomic network that regulates the binding of SRF/cofactor complex by using advanced techniques to discover the new mechanisms involved in cancer and CVD." (PMID 32885587, 2021). "More specifically, IGF2BP1 binds the 3′UTR of serum response factor (SRF) mRNA in an m6A-dependent manner and promotes SRF mRNA expression by impairing microRNA-dependent decay in several cancer cell lines." (PMID 32296573, 2020). "With the help of cofactors, IGF2BPs promote the stability of thousands of potential target mRNAs, hinder miRNA-induced RNA decay and improve the expression of oncogenes (MYC, Actin, Lin28, SRF) to play a carcinogenic role in cancer." (PMID 32653017, 2020). "Serum response factor (SRF) is a master regulator of several cellular processes including cancer cell growth, migration and angiogenesis." (PMID 32046103, 2020). "In view of recent reports, these findings suggested that IGF2BP1 promotes SRF expression in cancer by impairing the miRNA-dependent decay of the SRF mRNA." (PMID 30371874, 2019). "In conclusion, these findings suggest SRF/IGF2BP1-dependent gene expression as a novel therapeutic hub in cancer treatment." (PMID 30371874, 2019). "It is able to binds the SRF mRNA and promotes SRF expression in several cancer cell lines by impairing the miRNA-dependent decay of the SRF mRNA." (PMID 31208008, 2019). "Although SRF-promoter and IGF2BP1-3′UTR association appeared conserved for only 257 of 539 DN-transcripts, the vast majority of these mRNAs showed positively associated expression with SRF and IGF2BP1 in the four cancers analyzed." (PMID 30371874, 2019). "Here, we demonstrate that the mRNA-binding protein IGF2BP1 is a conserved post-transcriptional enhancer of SRF-driven transcription in cancer." (PMID 30371874, 2019).
cancer (continued). "Taken together, this suggests that IGF2BP1 promotes SRF-dependent transcription in a largely miRNome- and potentially m6A-dependent manner in cancer." (PMID 30371874, 2019). "The activity of both reporters was substantially diminished by the depletion of either IGF2BP1 or SRF in all cancer cells analyzed." (PMID 30371874, 2019). "The oncofetal mRNA-binding protein IGF2BP1 and the transcriptional regulator SRF modulate gene expression in cancer." (PMID 30371874, 2019). "Concomitantly, this observation underpins the physiological relevance of miRNA-directed control of SRF expression reported in cancer cells, endothelial and (smooth) muscle cells, e.g.." (PMID 30371874, 2019). "Among these were miRNAs or miR families like miR-22-3p, 125-5p or miR-181-5p that were previously reported to downregulate SRF expression in cancer, smooth muscle and/or endothelial cells." (PMID 30371874, 2019). "Both transcripts (FOXK1 and PDLIM7) were decreased upon the knockdown of IGF2BP1 suggesting a substantial conservation of SRF/IGF2BP1-dependent regulation of both factors in cancer cells." (PMID 30371874, 2019). "This suggested that IGF2BP1 depletion interferes with SRF/TCF- as well as SRF/MRTF-dependent transcriptional regulation in cancer cells mainly by reducing cellular SRF abundance." (PMID 30371874, 2019). "This was analyzed by monitoring the activity of SRF/TCF- and SRF/MRTF-dependent luciferase reports in cancer cells upon the depletion of IGF2BP1 or SRF." (PMID 30371874, 2019). "The Rho-GTPase Cdc42 was shown to similarly promote cancer cell transendothelial migration by regulating β1 integrin gene transcription through SRF-mediated activation." (PMID 29907768, 2018). "By using a panel of previously well-characterized cancer-associated pathway reporter analyses, we found at least four pathways, e.g., ELK1/SRF, AP1, STAT1/2, MYC/MAX, are significantly affected." (PMID 28099902, 2017). "In the present study, we demonstrated for the first time that SRF is overexpressed in stromal cells in GC tissues, and promotes migration/invasion of GC cells by facilitating myofibroblast-cancer cell crosstalk in an SDF1-CXCR4 dependent manner." (PMID 27323859, 2016). "In the present study, we further report that SRF is overexpressed in GC stromal myofibroblasts and promotes the invasion and migration of GC cells by facilitating myofibroblast-cancer cell crosstalk in an SDF1-CXCR4-dependent manner." (PMID 27323859, 2016). "It has been reported that the upregulation of SRF expression in GC cells promotes GC invasion/metastasis, and SRF is primarily expressed in cancer cells in GC tissues." (PMID 27323859, 2016). "As a master transcription factor that regulates the expression of over 200 genes, SRF is thought to promote cancer metastasis through a number of pathways." (PMID 27323859, 2016). "Taken together, our results suggest that SRF has potential as a chemotherapeutic agent for cancer treatment and provides an alternate scaffold for the development of improved anti-cancer agents." (PMID 25354194, 2014). "Taken together, our data confirm that SRF selectively targets cancer cells and is efficacious against several different cancer types." (PMID 25354194, 2014). "Intriguingly, SRF was found to selectively inhibit cancer cell proliferation and was effective against drug-resistant cancer cells by virtue of its ability to bypass the multidrug resistance transporter P-glycoprotein." (PMID 25354194, 2014). "Taken together, these observations further reiterate the fact that SRF selective targets cancer cells." (PMID 25354194, 2014). "Samples in the whole cancer data set (1881 patients) were stratified into three quantiles, low, intermediate and high, based on SRF-dependent/SAP-independent or SRF-independent/SAP-dependent gene expression." (PMID 24495796, 2014). "SRF activity in this in vitro EMT model is consistent with a possible physiologic response to wounding that is subverted in cancer cells." (PMID 23593114, 2013).